ADAMDEC1 (ADAM like decysin 1)
Description:
May play an important role in the control of the immune response and during pregnancy.
Synonyms: M12.219
Tractability: Antibody: UniProt places it where antibodies can reach, with medium confidence; UniProt predicts a signal peptide or a membrane-spanning region; its Gene Ontology location is reachable by antibodies, with medium confidence.
Gene: Protein-coding gene on chromosome 8 (24,384,285 to 24,406,013, forward strand). Ensembl gene ENSG00000134028.
Subcellular location: Secreted
Gene Ontology:
Molecular function: metalloendopeptidase activity; zinc ion binding; metallopeptidase activity
Biological process: immune response; negative regulation of cell adhesion; proteolysis
Cellular component: extracellular matrix; extracellular region
Genetic constraint (gnomAD): Loss-of-function variants: 43 observed, 44.94 expected, observed/expected ratio (o/e) 0.96, 90% interval 0.75 to 1.23. The upper end of that interval is the gene's LOEUF score, 1.23, which puts it in group 5 of 6, group 1 being the genes least tolerant of losing a copy. Missense variants: 498 observed, 503.94 expected, observed/expected ratio (o/e) 0.99, 90% interval 0.92 to 1.06. Synonymous variants: 181 observed, 176.2 expected, observed/expected ratio (o/e) 1.03, 90% interval 0.91 to 1.16.
Homologues: Orthologues: chimpanzee ADAMDEC1 (99% identical), macaque ADAMDEC1 (95% identical), dog ADAMDEC1 (79% identical), rabbit ADAMDEC1 (74% identical), pig ADAMDEC1 (73% identical), guinea pig ADAMDEC1 (71% identical), mouse Adamdec1 (65% identical), rat Adamdec1 (65% identical), zebrafish adam9b (24% identical), tropical clawed frog XB990656 (24% identical), Caenorhabditis elegans unc-71 (22% identical), zebrafish adam10a (21% identical), and 4 more. Paralogues in human: ADAM28 (43% identical), ADAM7 (31% identical), ADAM8 (31% identical), ADAM9 (29% identical), ADAM33 (28% identical), ADAM19 (28% identical), ADAM12 (27% identical), ADAM15 (26% identical), ADAM23 (25% identical), ADAM20 (24% identical), ADAM30 (24% identical), ADAM11 (23% identical), and 8 more.
Diseases named in the same sentence as ADAMDEC1 in open-access papers:
ADAMDEC1 is named in the same sentence as 45 diseases in open-access papers, as found by Europe PMC text mining. Sharing a sentence is not in itself a finding about the gene and the disease. The quoted sentences say what the papers report.
Crohn disease (8 papers, 2016 to 2025). A gastrointestinal disorder characterized by chronic inflammation involving all layers of the intestinal wall, noncaseating granulomas affecting the intestinal wall and regional lymph nodes, and transmural fibrosis. "As a metalloprotease, ADAMDEC1 is not only associated with a number of inflammatory diseases (including pulmonary sarcoidosis, atherosclerosis, and Crohn’s disease) but it also plays a key role in the pathogenesis of cancer." (PMID 35379209, 2022). "However, it must be noted that, increased levels of ADAMDEC1 have also been shown to be associated with the inflammation in Crohn’s disease and has also been reported to be highly expressed in Chronic rhinosinusitis with nasal polyps." (PMID 31467500, 2019). "In summary, ADAMDEC1 protects the bowel from chemical and bacterial insults, failure of which may predispose to Crohn’s disease." (PMID 27226416, 2016). "In summary, we identified ADAMDEC1 as a novel marker for intestinal inflammation and Crohn’s disease and it is selectively expressed in colonic mucosal PDGFRα+ cells." (PMID 35563399, 2022). "ADAMDEC1 protein was detected and was found at notably higher levels in Crohn’s disease-affected colonic tissue." (PMID 35563399, 2022). "This increase of both mRNA and protein of ADAMDEC1 in Crohn’s disease-affected colonic mucosa is consistent with our DSS-induced colitis mouse model." (PMID 35563399, 2022). "Conversely, our data shows that expression of both ADAMDEC1 mRNA and protein is indeed upregulated in Crohn’s disease patients." (PMID 35563399, 2022). "Using two different exon-spanning primer sets in RT-PCR, we found that while both healthy and Crohn’s disease affected colonic tissues expressed ADAMDEC1." (PMID 35563399, 2022). "Lastly, we examined if the upregulation of Adamdec1 observed in our DSS mouse colitis model is consistent in human tissue affected by Crohn’s disease." (PMID 35563399, 2022). "Expression of ADAMDEC1 was significantly increased in Crohn’s disease-affected colonic tissue compared to healthy colonic tissue." (PMID 35563399, 2022). "The identification of reduced ADAMDEC1 expression in Crohn’s disease patients has provided evidence of a potential role in bowel inflammation." (PMID 27226416, 2016). "Additionally, ADAMDEC1 was detected through immunohistochemistry within PDGFRα+ cells in Crohn’s disease-affected colonic mucosa." (PMID 35563399, 2022). "Although ADAMDEC1’s physiological roles are still largely unknown, a recent study has shown that this protein may have a protective effect against the development of Crohn’s disease." (PMID 35563399, 2022). "However, ADAMDEC1 has reduced levels of expression in macrophages in Crohn’s disease patients." (PMID 35563399, 2022). "In addition, the target gene of miR-7219-3p, Adamdec1, which protects the intestine from chemical and bacterial insults that may contribute to the development of Crohn’s disease, was also confirmed to be downregulated by probiotics in one study." (PMID 36304467, 2022). "In addition, we found that the ADAMDEC1 protein is mainly localized near the intestinal epithelium and is greatly induced in murine tissue affected by colitis as well as human colonic mucosa tissue from Crohn’s disease-affected patients." (PMID 35563399, 2022). "It is largely unknown how ADAMDEC1 plays a protective role in Crohn’s disease." (PMID 35563399, 2022). "The mRNA and protein expression of the Adamdec1 gene was induced in both DSS-induced colitis mouse models and human Crohn’s disease patients." (PMID 35563399, 2022). "ADAMDEC1 expression significantly increases in DSS-induced colitis affected mice and Crohn’s disease affected human tissue, suggesting that this gene can serve as a diagnostic and/or therapeutic target for intestinal inflammation and Crohn’s disease." (PMID 35563399, 2022). "Expression of Adamdec1 is induced in the DSS-induced colitis mouse model and human tissue affected by Crohn’s disease (unpublished data)." (PMID 30674925, 2019).
Crohn disease (continued). "ADAMDEC1 is a unique member of the ADAM (A Disintegrin And Metalloproteinase) family and is under-expressed in approximately 10% of Crohn disease patients." (PMID 28512356, 2017). "Our data suggest that study of the expression of ADAMDEC1 should be focused on PDGFRα+ cells in Crohn’s disease patients, and not in macrophages." (PMID 35563399, 2022). "Additionally, overexpression of both ADAMDEC1 mRNA and protein was consistently observed in PDGFRα+ cells, but not in CD64+ macrophages found in human colonic mucosal tissue affected by Crohn’s disease." (PMID 35563399, 2022).
colitis (7 papers, 2016 to 2025). Inflammation of the colon. "The loss of Adamdec1 rendered mice more susceptible to the induction of bacterial and chemical induced colitis, as evidenced by increased neutrophil infiltration, greater IL-6 and IL-1β secretion, more weight loss and increased mortality." (PMID 27226416, 2016). "Our data combined with the results of the transgenic Adamdec1 knockout phenotype indicate that induction of Adamdec1 may be a secondary defensive response to inflammation and that increased ADAMDEC1 contributes to loss of PDGFRα+ cells in DSS-induced colitis." (PMID 35563399, 2022). "Additionally, Adamdec1 knockout mice showed increased sensitivity to the DSS colitis, associated with neutrophilic (CD1B+ GR1+ F480−) infiltrate." (PMID 35563399, 2022). "Our analysis supports a critical role for the metalloprotease Adamdec1 at the interface between tissue remodeling and healing during colitis, demonstrating its requirement for colon epithelial integrity." (PMID 35085231, 2022). "We confirmed the expression of IL-6 and ADAMDEC1 in plasma samples from colitis, ileocolitis, ileitis, polyarteritis nodosa (Pan), ulcerative colitis (left-sided), idiopathic gastroparesis (IG) and diabetic gastroparesis (DG) by ELISA." (PMID 35563399, 2022). "Adamdec1 was predominantly expressed in CD45− PDGFRα+ cells in DSS-induced colitis mice, with only minimal expression in CD45+ CD64+ macrophages." (PMID 35563399, 2022). "Adamdec1 KO mice also presented with hyperplasia, edema, increased immune infiltrates, and muscle thickening, altogether indicative of colitis disease pathology." (PMID 35085231, 2022). "The exact mechanism by which ADAMDEC1 exerts this protective effect against colitis is yet to be determined." (PMID 27226416, 2016). "Adamdec1 has been shown to be upregulated in a DSS-induced colitis mouse model." (PMID 35563399, 2022). "Next, we examined expression changes of Adamdec1 in the DSS-induced colitis mouse model." (PMID 35563399, 2022). "Expression of Adamdec1 is upregulated in DSS-induced colitis models." (PMID 35563399, 2022). "We identified phenotypic and functionally divergent fibroblast populations in mucosal tissues of the gastrointestinal tract and uncovered molecular circuitries governing inflammation and ECM remodeling during colitis, identifying a key role for Adamdec1 in mucosal matrix remodeling and healing." (PMID 35085231, 2022). "We have demonstrated that in the absence of Adamdec1, mice are more susceptible to infection and colitis." (PMID 27226416, 2016). "EGR1 transcription is reduced during colitis, resulting in downregulation of KLK1 in goblet cells, which impairs mucosal barrier integrity and reduces Lys‐des‐Arg9‐BK levels, leading to upregulation of B1R in ADAMDEC1+ fibroblasts." (PMID 40859429, 2025). "PDGFRα+ cells significantly overexpressed Adamdec1 mRNAs and protein in DSS-induced colitis mice." (PMID 35563399, 2022).
colorectal cancer (7 papers, 2021 to 2025). A primary or metastatic malignant neoplasm that affects the colon or rectum. "On the other hand, high ADAMDEC1 IHC score in CAFs correlated with favorable outcomes in early-stage colorectal cancer." (PMID 40759242, 2025). "UTP3 was proved to be involved in the pathogenesis of colorectal cancer and ADAMDEC1 was a positive regulator of epithelial defense against cancer and plays an active role in inhibiting glioblastoma development." (PMID 33592580, 2021). "Several studies have shown that ADAMDEC1 as a prognostic factor in gastric adenocarcinoma and the mRNA expression of ADAMDEC1 is decreased during both tumorigenesis and tumor progression in colorectal cancer." (PMID 34893046, 2021). "The ADAM (a disintegrin and metalloprotease) gene-related family including ADAM, ADAMTS, and ADAM-like decysin-1 has been reported to play an important role in the pathogenesis of multiple diseases, including cancers (lung cancer, gliomas, colorectal cancer, and gastrointestinal cancer)." (PMID 36172139, 2022). "ADAMDEC1+ fibroblasts and MMP1+ CAFs were more abundant in primary colorectal cancer (mCC and nCC) than in metastatic liver cancer (mLC)." (PMID 41031085, 2025). "Here, using real gene expression data, we applied CSER to construct a colorectal cancer GRN and successfully identified several key regulatory genes closely related to colorectal cancer (CRC), including ADAMDEC1, CLDN8, and GNA11." (PMID 39371416, 2024). "To evaluate whether CAFs expressing Tr-CAF markers could inhibit tumor progression, we investigated the correlation between the CAF-specific immunohistochemical (IHC) staining levels for these 4 CAF markers; CXCL14, ADAMDEC1, EDNRB, and PROCR, and the clinical outcomes of colorectal cancer patients." (PMID 40759242, 2025).
glioma (3 papers, 2022 to 2023). A benign or malignant brain and spinal cord tumor that arises from glial cells (astrocytes, oligodendrocytes, ependymal cells). "Among them, ADAM9, ADAM12, ADAMTS7, ADAMTS9, and ADAMDEC1 were the proteases where increased expression associated with poorer prognosis of glioma patients." (PMID 36172139, 2022). "The high expression of ADAMDEC1 was significantly associated with advanced clinicopathological features and poor progression survival in glioma patients." (PMID 36172139, 2022). "More dead glioma patients corresponding to the higher risk score had more obvious correlation to the expression of ADAMDEC1." (PMID 36172139, 2022). "Therefore, our findings indicated that the high expression of ADAMDEC1 was positively associated with advanced clinicopathological features in glioma patients." (PMID 36172139, 2022). "Downregulation of ADAMDEC1 was shown to upregulate active caspases 3 and 9, inhibit proliferation and induce apoptosis in glioma cells." (PMID 37812190, 2023). "We constructed a risk model using HOXA5, PTPN2, WT1, HOXD10, POSTN, ADAMDEC1 and MYBPH expression data from a cohort of patients in TCGA, and found that it had significant prognostic value for ATRX-wt glioma patients." (PMID 37812190, 2023). "In the test cohort, HOXA5, PTPN2, WT1, HOXD10, POSTN, ADAMDEC1 and MYBPH levels were elevated in glioma tissues with high-risk scores." (PMID 37812190, 2023). "In glioma tissues from the high-risk group of the training cohort, HOXA5, PTPN2, WT1, HOXD10, POSTN, ADAMDEC1 and MYBPH were highly expressed." (PMID 37812190, 2023). "Nevertheless, HOXA5, PTPN2, WT1, HOXD10, POSTN, ADAMDEC1 and MYBPH were overexpressed in ATRX-mt glioma tissues with high-risk scores compared with low-risk scores." (PMID 37812190, 2023). "ADAMDEC1 showed a phenomenon of “abundance and disappear” expression in gliomas and normal tissues in that the higher the expression of ADAMDEC1 presented, the higher the malignancy of gliomas and the worse the prognosis." (PMID 36172139, 2022). "ADAM12 and ADAMDEC1 have an obvious impact on the prognosis of glioma patients through comprehensive analysis including overall survival and ADAMs expression levels." (PMID 36172139, 2022). "The mRNA and protein expression levels of ADAMDEC1 were upregulated in glioma tissues and cell lines." (PMID 36172139, 2022). "Then, we first examined ADAMDEC1 expression levels in glioma cell lines by Western blot, and LN229 of the glioma cell line was used in further experiments." (PMID 36172139, 2022). "ADAMDEC1 expression was primarily detected in the cytoplasm of glioma cells, and the staining intensity of ADAMDEC1 was increased in glioma tissues compared with normal tissues." (PMID 36172139, 2022). "Based on the important roles that ADAMDEC1 played in other cancers, this study investigated the contribution and prognostic signature of ADAMDEC1 in glioma." (PMID 36172139, 2022). "Combined with the presence and absence of ADAM family members’ expression in gliomas and the prognostic analysis, ADAMDEC1 had a great advantage in the prevention and treatment of gliomas, especially with the development of gene-targeted drugs." (PMID 36172139, 2022). "Here, we aimed to investigate the biological functions and potential mechanism of ADAMDEC1 in gliomas." (PMID 36172139, 2022). "In the present study, we found that the expression levels of ADAMDEC1 were significantly elevated compared with other ADAMs by analyzing the expression levels of ADAM family proteins in gliomas." (PMID 36172139, 2022). "Our results also showed that overexpression of ADAMDEC1 promoted the invasiveness of glioma LN229 cells, while the number of cells in the shRNA-ADAMDEC1 group was reduced." (PMID 36172139, 2022). "For central nervous system tumors, it was found that ADAMDEC1 expression level was significantly higher than the control group in either enamel epithelial craniopharyngioma or squamous papillary craniopharyngioma." (PMID 36172139, 2022).
glioma (continued). "To investigate the effects of overexpression or silencing of ADAMDEC1 on proliferation, migration, and invasion of glioma LN229 cells, we first used CCK-8 cell proliferation assay to confirm that overexpression of ADAMDEC1 enhanced cell proliferation and increased with time (p < 0.05)." (PMID 36172139, 2022). "This suggests that ADAMDEC1 has potential as a glioma clinical marker and immunotherapy target." (PMID 36172139, 2022). "Three immunoassays (TIMER, MCPCOUNTER, and XCELL) were used to determine whether ADAMDEC1 affects tumor progression through inflammatory responses in gliomas." (PMID 36172139, 2022). "TCGA data also demonstrated ADAMDEC1 mRNA levels in different types of gliomas." (PMID 36172139, 2022). "As we found, ADAMDEC1 had co-expression with MMP2 in gliomas." (PMID 36172139, 2022). "Our data suggested that ADAMDEC1 could serve as a glioma clinical marker and immunotherapy target." (PMID 36172139, 2022). "ADAMDEC1 is rarely expressed in grade I and grade II gliomas, but highly expressed in grade III and grade IV gliomas." (PMID 36172139, 2022). "A receiver operating characteristic curve analysis indicated that HOXA5, PTPN2, WT1, HOXD10, POSTN, ADAMDEC1 and MYBPH had significant prognostic value for the survival of ATRX-wt glioma patients (AUC = 0.84, 0.81, 0.79, 0.91, 0.80, 0.79 and 0.85, respectively)." (PMID 37812190, 2023). "In conclusion, our study revealed that an immune signature based on HOXA5, PTPN2, WT1, HOXD10, POSTN, ADAMDEC1 and MYBPH expression effectively predicted the prognosis of ATRX-wt glioma patients, and demonstrated that immunotherapy was effective for low-risk patients." (PMID 37812190, 2023). "The differences between the presence and absence of ADAMTS20 and ADAMDEC1 had obvious advantages in the prevention and identification of glioma in clinical treatment." (PMID 36172139, 2022). "Among them, ADAMTS20 and ADAMDEC1 showed no expression in normal brain tissue, but their expression was significantly increased in glioma." (PMID 36172139, 2022). "Using the bioinformatics database TCGA, we found that ADAMDEC1 was not present in normal brain tissues compared with the tissues from glioma patients." (PMID 36172139, 2022). "ADAMDEC1 was positively correlated with MMP2, and we predicted that ADAMDEC1 could regulate the proliferation and invasion of glioma cells by affecting the expression of MMP2." (PMID 36172139, 2022).
rosacea (3 papers, 2021 to 2023). A chronic erythematous skin disorder that affects the face. "Previous studies showed that GBP5 and ADAMDEC1 played a pro-inflammatory role in rosacea-like skin inflammation by regulating the M1 macrophage polarization." (PMID 38250077, 2023). "Furthermore, in terms of the effect of STAT1/IRF1 on M1 polarization, our previous study found that ADAMDEC1 plays a pro-inflammatory role in rosacea by modulating the M1 polarization of macrophages." (PMID 34290700, 2021). "Although the role of ADAMDEC1 has not been investigated in RA, its ability to induce inflammation in RA may be achieved by modulating the polarization of M1 macrophages as described in rosacea." (PMID 35379209, 2022).
bacteremia (2 papers, 2017 to 2022). "Furthermore, the removal of the Adamdec1 gene in mice induces a severe inflammatory response and bacteremia, which increases mortality, suggesting a protective role of ADAMDEC1 against bacterial insults into mucosa." (PMID 35563399, 2022). "In the absence of Adamdec1, greater numbers of Citrobacter rodentium were found in the spleen, suggestive of a breakdown in mucosal immunity that resulted in bacteremia." (PMID 28512356, 2017).
Colon Cancer (2 papers, 2022 to 2025). "CXCL14+ADAMDEC1+ fibroblast can be further divided into three subgroups (ADAMDEC1+CCL13hi, ADAMDEC1+FABP4hi, ADAMDEC1+SFRP1hi), all of which were significantly reduced in colon cancer tissue." (PMID 36463319, 2022).
systemic lupus erythematosus (2 papers, 2022 to 2024). An autoimmune multi-organ disease typically associated with vasculopathy and autoantibody production. "The close correlation between ADAMDEC1 and ADAM28 in systemic lupus erythematosus (SLE) regulates the disease inflammatory process." (PMID 35514959, 2022).